FLT3LG (fms related receptor tyrosine kinase 3 ligand)
Description:
Stimulates the proliferation of early hematopoietic cells by activating FLT3. Synergizes well with a number of other colony stimulating factors and interleukins. Required for the development of B cells, and dendritic cells (DCs).
Synonyms: Flt3L; FL; FLG3L; IMD125
Tractability: Small molecule: it has a binding pocket of medium quality. Antibody: its Gene Ontology location is reachable by antibodies, with high confidence; UniProt places it where antibodies can reach, with medium confidence; UniProt predicts a signal peptide or a membrane-spanning region. PROTAC: ubiquitination databases record sites on it.
Gene: Protein-coding gene on chromosome 19 (49,474,150 to 49,486,233, forward strand). Ensembl gene ENSG00000090554.
Subcellular location: Cell membrane (Isoform 1); Secreted (Isoform 2)
Pathways (Reactome):
Immune System: FLT3 Signaling; FLT3 signaling through SRC family kinases; Negative regulation of FLT3; STAT5 Activation
Signal Transduction: PI3K Cascade; PI5P, PP2A and IER3 Regulate PI3K/AKT Signaling; PIP3 activates AKT signaling; RAF/MAP kinase cascade
Disease: Constitutive Signaling by Aberrant PI3K in Cancer; FLT3 signaling by CBL mutants
Gene Ontology:
Molecular function: protein binding; receptor tyrosine kinase binding; signaling receptor binding; cytokine activity
Biological process: B cell differentiation; dendritic cell differentiation; embryonic hemopoiesis; positive regulation of cell population proliferation; signal transduction; positive regulation of natural killer cell proliferation
Cellular component: cell surface; cytosol; extracellular region; membrane; plasma membrane
Genetic constraint (gnomAD): Loss-of-function variants: 8 observed, 27.79 expected, observed/expected ratio (o/e) 0.29, 90% interval 0.17 to 0.52. The upper end of that interval is the gene's LOEUF score, 0.52, which puts it in group 2 of 6, group 1 being the genes least tolerant of losing a copy. Missense variants: 278 observed, 298.69 expected, observed/expected ratio (o/e) 0.93, 90% interval 0.84 to 1.03. Synonymous variants: 123 observed, 131.14 expected, observed/expected ratio (o/e) 0.94, 90% interval 0.81 to 1.09.
Homologues: Orthologues: chimpanzee FLT3LG (99% identical), macaque FLT3LG (95% identical), dog FLT3LG (71% identical), rat Flt3lg (69% identical), pig FLT3LG (69% identical), mouse Flt3l (68% identical), guinea pig FLT3LG (54% identical).
Diseases named in the same sentence as FLT3LG in open-access papers:
FLT3LG is named in the same sentence as 156 diseases in open-access papers, as found by Europe PMC text mining. Sharing a sentence is not in itself a finding about the gene and the disease. The quoted sentences say what the papers report.
melanoma (61 papers, 2011 to 2025). A malignant, usually aggressive tumor composed of atypical, neoplastic melanocytes. "In solid tumors such as malignant melanoma, colorectal cancer and breast cancer, FLT3LG can increase immune cell activity and elicit antitumor responses through the use of diverse modalities, such as plasmids, adenoviruses, vaccines, and adjuvants." (PMID 40329265, 2025). "A clinical trial is currently underway to treat melanoma patients with a combination of immunostimulatory FLT3LG and a peptide-based vaccine targeting DCs." (PMID 31620363, 2019). "To test these associations in different tumor types, we selected three T/NK cell modules (FLT3LG.mod, PDCD1.mod and FOXP3.mod that were associated with patient survival (in melanoma, head and neck and bladder tumors, respectively)." (PMID 26398410, 2015). "To explore in greater detail the extent of genetic alteration in melanoma samples selected for expression of FLT3LG.mod genes, we plotted p-values versus chromosomal location for all genes on chromosome 9p2." (PMID 26398410, 2015). "Melanoma, head and neck, and bladder tumors expressing high levels of FLT3LG.mod, PDCD1.mod and FOXP3.mod transcripts, respectively, also expressed significantly higher levels of LCK protein." (PMID 26398410, 2015). "Furthermore, the potential of FLT3LG to enhance tumor immunotherapy efficacy has been demonstrated in various tumor types, such as glioma, melanoma, breast cancer, and colorectal cancer, as supported by previous studies." (PMID 40329265, 2025). "To test this possibility, we identified four representative T/NK modules that tracked with survival differences in distinct tumor types (FOXP3.mod, PDCD1.mod, FLT3LG.mod and KLRB1.mod for bladder, head and neck, kidney and melanoma, respectively)." (PMID 26398410, 2015). "Recent studies of melanoma model mice and the TCGA melanoma dataset have shown that infiltration of cDC1 in the tumor is induced by XCL1, CCL5, or FMS-like tyrosine kinase 3 ligand (FLT3LG), which are produced by the NK cells infiltrated in the tumor." (PMID 37046775, 2023). "Supporting this data, the combination of NK and DC tumor gene signatures from The Cancer Genome Atlas correlated with melanoma patient survival, while NK cells in melanoma predicted response to anti-PD1 by regulating the DC abundance in tumors through secretion of cytokine FLT3LG." (PMID 30899263, 2019).
leukemia (19 papers, 2014 to 2025). A malignant (clonal) hematologic disorder, involving hematopoietic stem cells and characterized by the presence of primitive or atypical myeloid or lymphoid cells in the bone marrow and the blood. "FLT3LG studies in the biomedical literature are more related to leukaemia than musculoskeletal diseases." (PMID 37853468, 2023). "In the AML_GSE116256 dataset, FLT3LG is mainly expressed in CD4+ T cells, but compared with the PBMC_30K_10× dataset, the expression level of FLT3LG is remarkably reduced, and FLT3 is mainly expressed in leukemia cells and precursor cells." (PMID 36081495, 2022). "In general, our results demonstrate that IFITM3P6 and FLT3LG might serve as prognostic markers in AML and may be used as potential therapeutic targets for the treatment of leukemia in the future." (PMID 36081495, 2022).
glioma (15 papers, 2010 to 2025). A benign or malignant brain and spinal cord tumor that arises from glial cells (astrocytes, oligodendrocytes, ependymal cells). "FLT3LG seems to exert its anti-tumor activity in conjunction with macrophages and CD4 + T-cells in glioma, supporting the observation of a specific immune-modulatory effect of CIR." (PMID 35158950, 2022).
glioblastoma (8 papers, 2020 to 2025). The most malignant astrocytic tumor (WHO grade IV). "Genes that show higher expression in astrocytoma compared to glioblastoma were CX3CL1, CSF1 (MCSF), CCL3 (MIP1α), CCL4 (MIP1β), TGFα, FLT3LG, CXCL5, CCL19 while KITLG (SCF) and NGF were equally expressed in the two tumor types." (PMID 35301393, 2022).
viral infection (8 papers, 2010 to 2025). "Like the enrichment analysis of DEGs mentioned earlier, KEGG analysis of co-expressed genes revealed a close association between FLT3LG and immune pathways, particularly those related to T cells, natural killer (NK) cells and virus infection." (PMID 40329265, 2025).
acute myeloid leukemia (7 papers, 2017 to 2025). Acute myeloid leukemia (AML) is a group of neoplasms arising from precursor cells committed to the myeloid cell-line differentiation. "For instance, a study in the context of acute myelocytic leukemia showed that FLT3LG, along with IFITM3P6, correlates with T-cell activation in the bone marrow microenvironment and impacts patient survival." (PMID 39465855, 2024).
autoimmune disease (7 papers, 2008 to 2024). A disorder resulting from loss of function or tissue destruction of an organ or multiple organs, arising from humoral or cellular immune responses of the individual to their own tissue constituents. "FLT3LG stimulates the differentiation and proliferation of dendritic cells and has a potential therapeutic value in treating autoimmune diseases and tumors." (PMID 38212778, 2024). "FLT3LG is also a cytokine known to be involved in the mobilization and differentiation of hematopoietic stem cells and it has been linked to autoimmune disorders, but previously not to GD and TED." (PMID 35675127, 2022).
Autoimmunity (5 papers, 2013 to 2025). The occurrence of an immune reaction against the organism's own cells or tissues. "Hence, initial investigations concerning FLT3LG in the clinical domain have similarly prioritized hematological malignancies or autoimmune disorders." (PMID 40329265, 2025).
lung fibrosis (5 papers, 2022 to 2025). "Additionally, FLT3LG and FLT3 have been implicated in kidney and splenic fibrosis in mouse models, although their connection to lung fibrosis remains underexplored." (PMID 40165483, 2025).
pancreatic cancer (5 papers, 2020 to 2025). "Further analysis showed that the intratumour level of FLT3LG and CD40LG were positively correlated with αDC and tumour-resident DC scores in human pancreatic cancers." (PMID 37433774, 2023).
cervical cancer (4 papers, 2022 to 2025). A primary or metastatic malignant neoplasm involving the cervix. "Meanwhile, a clinical study on cervical cancer found that decreased FLT3LG expression is linked to a poor prognosis." (PMID 40072746, 2025). "In contrast, we validated the expression levels of FLT3LG at single cell resolution and found that it was upregulated mainly in cancer cells, which indicated its distinct function in cervical cancer." (PMID 36816023, 2023).
lung cancer (4 papers, 2023 to 2025). A malignant neoplasm involving the lung. "To ascertain the functional role of FLT3LG in vivo, we conducted an experiment in which FLT3LG was overexpressed in the mouse lung cancer cell line LLC." (PMID 40329265, 2025). "However, the specific function and potential mechanism of FLT3LG in lung cancer immunotherapy have yet to be investigated." (PMID 40329265, 2025). "Additionally, first clinical trials show the activity of FLT3LG in combination with stereotactic radiotherapy in non‐small cell lung cancer." (PMID 38327131, 2024).
prostate carcinoma (4 papers, 2021 to 2024). A carcinoma that arises from epithelial cells of the prostate gland. "Similarly, higher FLT3LG was associated with a lower risk of prostate cancer in both observational and exGS analyses." (PMID 38750076, 2024). "Therefore, lower FLT3LG may serve as a potential biomarker of early cancer processes leading to diagnosis among carriers of established prostate cancer risk variants." (PMID 38750076, 2024). "that demonstrated the important role of NK production of FLT3LG for protection/survival of DC precursors from prostate cancer-induced inhibition in vivo." (PMID 33665363, 2021). "Three proteins were associated with risk of prostate cancer: GP2, TSPAN1, and FLT3LG [1.29 (1.21–1.36), 1.14 (1.09–1.18), and 0.87 (0.82–0.92)] and three were associated with endometrial cancer: CHRDL2, KLK4, and WFIKKN1 [1.42 (1.21–1.65), 1.41 (1.20–1.65), and 1.42 (1.20–1.68)]." (PMID 38750076, 2024).
rectal cancer (3 papers, 2019 to 2022). A primary or metastatic malignant neoplasm that affects the rectum. "According to one study, increased circulating fms-related tyrosine kinase 3 ligand (FLT3LG) caused by neoadjuvant cytotoxic treatment in rectal cancer patients activated the anti-tumor immune response." (PMID 36348319, 2022).
bladder tumor (2 papers, 2015 to 2024). "Therefore, we further analyzed the role of FLT3LG in T-cell activation during BCG treatment in the MB49 bladder tumor-bearing mouse model." (PMID 38213738, 2024).
graft versus host disease (2 papers, 2018 to 2021). An immune system disorder that occurs after allogeneic hematopoietic stem cell transplant and is a reaction of donor immune cells against host tissues. "Five out of the six surviving NRG-HIS/Flt3LG mice, but none of the NRGF-HIS/Flt3L mice, developed significant graft versus host disease (GVHD) by day 20 following infection, which was likely due to the priming of allogeneic T cell responses by the Flt3LG-expanded murine DCs activated by YFV-17D." (PMID 30487575, 2018).
bladder cancer (1 paper, 2024). "Enrichment analysis of gene ontology biological processes in bladder cancer also indicated that FLT3LG is involved in T-cell activation, leukocyte cell‒cell adhesion, and regulation of the immune effector process." (PMID 38213738, 2024). "The bioinformatics analysis above revealed that FLT3LG is involved in T-cell activation during the development of bladder cancer and is positively correlated with several effector T-cell subtypes." (PMID 38213738, 2024). "This study highlights the critical role of FLT3/FLT3LG in BCG immunotherapy for bladder cancer and provides novel candidate targets for optimizing BCG immunotherapy in future studies." (PMID 38213738, 2024). "The results showed that in bladder cancer, FLT3LG not only exhibited significant positive correlations with immune checkpoints (CTLA416, IDO117), cytokines and chemokines (TNFSF13B, TNFRSF14, CXCR3, CCL4) but also exhibited the closest association with genes related to HLA18." (PMID 38213738, 2024). "Therefore, we further analyzed the biological processes in which FLT3LG is involved in the bladder cancer microenvironment." (PMID 38213738, 2024). "Here, we propose the hypothesis that during BCG immunotherapy for bladder cancer, immune activation can lead to a significant amount of FLT3LG secretion, which in turn activates cytotoxic CD8+ T cells within the tumor to exert antitumor activity." (PMID 38213738, 2024).
head and neck squamous cell carcinoma (1 paper, 2024). A squamous cell carcinoma that arises from any of the following anatomic sites: lip and oral cavity, nasal cavity, paranasal sinuses, pharynx, larynx, and salivary glands. "Increased CD28 expression has been shown to correlate with improved survival in head and neck squamous cell carcinoma (HNSCC), while increased FLT3LG expression has previously been shown to correlate with improved survival in cervical cancer." (PMID 39672307, 2024).
lung adenocarcinoma (1 paper, 2025). A carcinoma that arises from the lung and is characterized by the presence of malignant glandular epithelial cells. "Furthermore, FLT3LG is closely associated with the functions of diverse immune cell types and is significantly positively correlated with the extent of immune cell infiltration, especially in lung adenocarcinoma (LUAD)." (PMID 40329265, 2025). "Compared with that in normal tissues, FLT3LG expression is significantly downregulated in 13 types or subtypes of tumors, including lung adenocarcinoma (LUAD) and lung squamous cell carcinoma (LUSC)." (PMID 40329265, 2025). "Moreover, high expression of FLT3LG was significantly positively correlated with increased infiltration of multiple immune cells, including T cells and natural killer (NK) cells, in lung adenocarcinomas, as well as the expression of several immune cell markers, such as CD4 and CD8a." (PMID 40329265, 2025).
skin cutaneous melanomas (1 paper, 2021). "Notably, we found a strong correlation of FLT3LG and CCL5 expression in the case of metastatic human skin cutaneous melanomas (M-SKCM), BRCAs and CESCs." (PMID 33980589, 2021).
thyroid cancer (1 paper, 2025). "This aligns with the findings of our MR analysis, which determined that genetically predicted circulating FLT3LG acts as a protective factor against thyroid cancer." (PMID 40072746, 2025). "Additionally, there was a notable association between levels of FGF19, IL2RB, TNFRSF9, S100-A12, FLT3LG, and CCL19 and a decreased risk of thyroid cancer." (PMID 40072746, 2025). "Consequently, it is essential to investigate the feasibility of combining FLT3LG with immunotherapy methods and to elucidate relationships between FLT3LG and the prognosis of thyroid cancer patients in future studies." (PMID 40072746, 2025).
tumor (249 papers, 2007 to 2026). "FLT3LG is regarded as being associated with tumor diagnosis and immunotherapy in a variety of tumor types, but its function in LUAD is uncertain." (PMID 40329265, 2025). "Using tumor cell lines stably expressing FLT3LG, it has been confirmed that the antitumor effect of FLT3LG in these cases is associated with the expansion of DCs in lymphoid and peripheral tissues and activation of tumor antigen-specific T cells." (PMID 38213738, 2024). "Further studies have demonstrated that the abundance of cDC1s surrounding tumor cells and their activity directly depend on the expression of the gene encoding Fms-related tyrosine kinase-3 ligand (FLT3LG) whose intra-tumoral production is regulated by NKs." (PMID 31750245, 2019). "In humans, genes encoding for FLT3LG within the tumor are linked to NK cell presence." (PMID 33679726, 2020). "Consequently, further investigations into the underlying mechanism of FLT3LG and tumor immunity may provide novel insights for improving the prognosis of LUAD patients." (PMID 40329265, 2025). "The findings revealed that, compared with that in normal lung tissues, FLT3LG expression in tumor tissues was significantly lower in NSCLC patients." (PMID 40329265, 2025). "Increased expression of FLT3LG significantly enhanced the infiltration of multiple immune cells, particularly T cells and NK cells, into the tumor microenvironment." (PMID 40329265, 2025). "In the initial stage of tumor development (T1), a greater percentage of patients exhibited higher expression of FLT3LG, whereas in the subsequent stages (T2, T3 and T4) was opposite." (PMID 40329265, 2025). "Similar findings were obtained by combining a PD-1 blocker plus recombinant fms related receptor tyrosine kinase 3 ligand (FLT3LG) – together mediating a minimal activity on tumor growth and OS – with focal RT delivered in 3 fractions of 10 Gy." (PMID 39873285, 2025). "In this study, we transfected lentiviruses to construct mouse LLC cells with elevated expression of FLT3LG and subsequently used these cells to establish a subcutaneous transplantation tumor model in the axilla, a lymphoid tissue-rich region." (PMID 40329265, 2025). "Our findings revealed that FLT3LG primarily participated in tumor immune-related functions and pathways within the context of LUAD." (PMID 40329265, 2025). "Since a significant decrease in FLT3LG expression was observed in the tumor tissues of NSCLC patients, we investigated the potential associations between FLT3LG expression and the clinicopathological characteristics of NSCLC patients." (PMID 40329265, 2025). "To investigate the function of FLT3LG in different cancers, we first performed a pan-cancer analysis of FLT3LG in 8112 tumor and 1520 normal samples from the TCGA database." (PMID 40329265, 2025). "In this study, we explored the significance of FLT3LG in NSCLC, particularly in LUAD for diagnostic and prognostic purposes, as well as its potential involvement in tumor development, utilizing databases such as TCGA and TIMER." (PMID 40329265, 2025). "In recent years, reports have indicated that FLT3LG can facilitate the proliferation of immune cells, impede tumor growth either directly or indirectly, and augment the effectiveness of anti-PD-1 therapy in solid tumors." (PMID 40329265, 2025). "To evaluate the immune function of FLT3LG in vivo, we established a mouse subcutaneous graft tumor model." (PMID 40329265, 2025). "Since tumor PD-L1 expression significantly influences the response of patients to immunotherapy, we conducted an initial verification of the correlation between serum FLT3LG expression and PD-L1 expression in clinical tumor tissue samples." (PMID 40329265, 2025). "In the analysis of FLT3LG and the tumor microenvironment, FLT3LG showed positive correlations with immune checkpoints, CD8+ T-effector cells, and antigen processing machinery in BLCA." (PMID 38213738, 2024).